CD24 (CD24 molecule)
Diseases named in the same sentence as CD24 in open-access papers (continued):
Sharing a sentence is not in itself a finding about the gene and the disease.
prostate carcinoma (continued). "Immunohistochemical studies have reported the usefulness of anti-CD24 for detecting prostate cancer over the full range of prostate specimens encountered in surgical pathology, e.g. needle biopsies, transurethral resection of prostate chips, or prostatectomies." (PMID 16539730, 2006). "Gene-expression profiling of DU145 prostate cancer cells stimulated with HGF revealed induction of a molecular signature associated with stem cells, characterized by up-regulation of CD49b, CD49f, CD44 and SOX9, and down-regulation of CD24 (‘stem-like signature’)." (PMID 22110593, 2011). "The researchers identified six markers exhibiting significant alterations in prostate cancer cells compared to BPH epithelial cells, and among them, CD24 demonstrated a notable increase (2.18X)." (PMID 39687458, 2024). "Studies regarding CSC markers in prostate cancer are ongoing and CD44 and CD24 are promising candidates." (PMID 34206049, 2021). "CD24 showed positive cytoplasmic expression in both canine cells (PC1 and PC2) and the human prostate cancer PC3 cell line." (PMID 33806857, 2021). "To address this, we examined the expression of three reported prostate cancer stem cells markers, CD44, CD24 and Integrin α2β1, by the OPCT-1 clones." (PMID 28094783, 2017). "Here, we studied the expression of CD24 in tumors of MMTV-PyMT, Apc1572/T+ and TRAMP genetic mouse models that spontaneously develop mammary or prostate carcinoma, respectively." (PMID 26978528, 2016). "In breast and prostate cancer in particular, the subpopulation of cancer cells with stem-like properties is identified as being enriched in the CD44+/CD24- fraction." (PMID 27457474, 2016). "The recent identification of the IGS as a prognostic indicator in prostate cancer and the correlation with its presence in a subset of the LNCaP cell line, suggest that CD44+CD24− LNCaP cells can serve as a model system." (PMID 18268494, 2008). "A similar approach was used to unmask CD24 as a significant predictor of PSA relapse and poor prognosis in low-grade prostate cancer." (PMID 16539730, 2006). "Compared to non-cancer BPH tissue, prostate cancer samples demonstrated a statistically significant decrease in CD24+ cell numbers (p = 0.029, Kruskal-Wallis test)." (PMID 34019593, 2021). "CD38 was the most abundantly expressed marker and similarly to CD24 demonstrated a statistically significant decrease in prostate cancer samples compared to non-cancer tissue (p<0.01, Kruskal-Wallis test)." (PMID 34019593, 2021). "GOLM1, CD24, PSCA, and the gene fusion TMPRSS2-ERG were selected as overexpressed mRNAs in prostate cancer, whereas ANXA3 and SLC45A3 were selected as underexpressed mRNAs in prostate cancer for evaluation." (PMID 33172003, 2020). "High expression of CD44 with low/no expression of CD24 in prostate cancer cells has been reported to have high tumour initiating capacity in prostate cancer cell models." (PMID 28094783, 2017). "Our findings that CD24+ NPC cells are more invasive than parental or CD24− NPC cells are consistent with results from previous studies on CSCs in pancreatic, lung, and prostate cancer." (PMID 24955581, 2014). "Although some previous studies demonstrated the role of CD24 immunoexpression as a prognostic factor in human prostate cancer, CD24 gene expression performed in this study did not validate this hypothesis." (PMID 33806857, 2021). "In conclusion, our data demonstrate that while CD24 is distinctively but diversely expressed during tumor development in genetic models of breast and prostate cancer, lack of CD24 did not significantly influence tumor initiation and only partly affected tumor burden in these models." (PMID 26978528, 2016).
prostate carcinoma (continued). "A non-malignant cell line RWPE-1 as well as prostate cancers PC-3 and DU145 demonstrated the CD44+/CD24- and CD44+/CD24+ phenotypes of progenitor cells, while prostate cancers 22Rv1 and LNCaP demonstrated CD44-/CD24- and CD44-/CD24+ phenotypes." (PMID 34019593, 2021).
lung carcinoma (49 papers, 2003 to 2025). "Through previous studies, our research group has confirmed that CD24 is an independent prognostic risk factor for lung cancer patients." (PMID 41195275, 2025). "Our analysis identified the expression of CD27 on class-switched memory B cells and IgD+ CD24+ B cells as potential risk factors for lung cancer, using a Bonferroni-adjusted significance threshold of PBonferroni < 0.1." (PMID 38408977, 2024). "CD27 on class-switched memory B cells and IgD+ CD24+ B cells were potential risk factors for lung cancer." (PMID 38408977, 2024). "Expanding on this, Qiao (2021) demonstrated that high expression of CD24, along with Hsp70 (a molecular chaperone), is associated with poor survival in lung cancer." (PMID 39595659, 2024). "Since increased expression of CD24 is associated with poorer prognosis in lung cancer, a corresponding role in lung cancer is likely." (PMID 38870055, 2024). "CD27 on CD24+ CD27+ B cell was identified to increase the risk of lung cancer in our research." (PMID 38408977, 2024). "Besides, a strong association was observed between CD24 amplification and OS of lung cancer patients." (PMID 31244889, 2019). "Additionally, the increase of CD27 on switched memory B cells and CD27 on IgD+ CD24+ B cells may be linked to lung cancer development." (PMID 38408977, 2024). "The binding of Hsp70 to CD24 promotes the invasion and metastasis of lung cancer through the MAPK/ERK signaling pathway." (PMID 41195275, 2025). "Collectively, these findings demonstrate that Hsp70 knockdown suppresses oncogenic phenotypes in lung cancer cells, whereas CD24 overexpression enhances malignant progression." (PMID 41195275, 2025). "To evaluate the functional roles of Hsp70 and CD24 in lung cancer metastasis, we established a xenograft model via tail vein injection in immunocompromised mice (n = 6 per group)." (PMID 41195275, 2025). "The results showed that the expression of Hsp70 and CD24 in lung cancer tissues was significantly higher than that in paracancerous tissue, and high expression of Hsp70 and CD24 suggested a poor prognosis for patients." (PMID 41195275, 2025). "To further investigate the effects of Hsp70 and CD24 on the malignant biological behavior of lung cancer cells, we overexpressed CD24 in H1975 and A549 cells following HSP70 knockdown." (PMID 41195275, 2025). "We found that heat shock protein 70 (Hsp70) and cluster of differentiation 24 (CD24) are highly expressed in lung cancer tissues and cells." (PMID 41195275, 2025). "To investigate the effects of Hsp70 knockdown and CD24 overexpression on the malignant biological behavior of lung cancer cells, we conducted a series of cellular phenotype experiments." (PMID 41195275, 2025). "Our research group has confirmed that CD24 and Hsp70 jointly affect the prognosis of lung cancer patients." (PMID 41195275, 2025). "The results showed that CD24 overexpression promoted the distant metastasis of lung cancer in nude mice, while Hsp70 knockdown had the opposite effect." (PMID 41195275, 2025). "CD24 is one of the client proteins of Hsp70, forming protein complexes with it to promote the invasion and metastasis of lung cancer." (PMID 41195275, 2025). "This study identifies HSP70 as a critical upstream regulator of CD24 in lung cancer, demonstrating a unidirectional regulatory relationship wherein HSP70 controls CD24 expression without reciprocal feedback." (PMID 41195275, 2025). "The discovery of 106 immune signatures, particularly five key associations such as CD25 on IgD- CD24- cells in SCLC and CCR2 on monocyte cells in LUSC, enriches our understanding of these cells’ causal involvement in lung cancer." (PMID 38962009, 2024). "Causal effects between CD27 on CD24+ CD27+ cells and CD27 on memory B cells with lung cancer subtypes." (PMID 38962009, 2024).
lung carcinoma (continued). "The tLyp-1-Lam2b-siSOX2 exosomes were efficiently taken up by lung cancer cells, which led to effective knockdown of the SOX2 gene and decreased the stem cell population of lung cancer cells (CD44+/CD24− cells)." (PMID 39355533, 2024). "Karimi-Busheri (2013) further identified the CD24+/CD38− phenotype as a potential biomarker for non-small cell lung cancer, collectively suggesting that CD24 plays a significant role in lung cancer development and progression." (PMID 39595659, 2024). "In immunohistochemistry experiments, the expression levels of multiple genes, including CHCHD2, CEACAM5, GAPDH, and CD24, were significantly upregulated in lung cancer tissues compared to normal tissues." (PMID 38872167, 2024). "As expected, at the protein expression level, we found that the expression of CD47 and CD24 in lung tissue of lung cancer mice was significantly increased compared with healthy mice." (PMID 36186906, 2022). "In the human lung carcinoma model A549, CD24 expression increased the expression of p-STAT3 (Y705), p-FAK (Y925), and p-Src (Y416) via Src, therefore it is associated with a poor prognosis of cancer." (PMID 31614769, 2019). "The significance of CD24 amplification is further enhanced as the frequency of CD24 amplification is relatively high among major cancer types, including breast (18.4%), ovarian (20.3%), and lung cancer (19.6%)." (PMID 31244889, 2019). "More importantly, proliferation index of lung cancer cells, SP+ LCSCs ratio and CD24+IGF1R+ LCSCs ratio in CTX+SHSB group were remarkably lower than that in control and CTX groups." (PMID 28977934, 2017). "Previous studies on several types of human cancers – including breast, brain and lung cancers – have identified a group of cells called CD44+/CD24- cells that seem to be more aggressive and resistant to therapy than other cancer cells." (PMID 28092266, 2017). "Lung cancer stem cells (LCSCs) are responsible for the initiation, progression, metastasis and relapse of lung cancers (e.g. SP+ LCSCs, CD24+IGF1R+ LCSCs and CD133+ LCSCs)." (PMID 28977934, 2017). "Shuanghuang Shengbai further decreased the ratios of SP+ and CD24+IGF1R+ lung cancer stem cells (P<0.05)." (PMID 28977934, 2017). "In tumour tissue of primary lung carcinomas, CD24 immunoreactivity was observed in 68 (76%) cases with a cytoplasmic and membraneous staining pattern." (PMID 12610508, 2003). "We aimed to determine the rate of CD24 expression in our nonsmall cell lung cancer (NSCLC) collection and to clarify its correlation with clinicopathological parameters including patients' survival." (PMID 12610508, 2003). "We further studied the mechanism of the involvement of Hsp70 and CD24 in lung cancer." (PMID 41195275, 2025). "Moreover, we observed an association between CD27 on CD24+ CD27+ B cells and increased lung cancer risk." (PMID 38408977, 2024). "However, there is also a notable gap in the research concerning the direct impact of CD27 expression on IgD+ CD24+ B cells in the context of lung cancer development." (PMID 38408977, 2024). "Additionally, it was found that CD24 was found to be generally elevated in the epithelial cells of lung cancer." (PMID 37187731, 2023). "Overall, HIIT combined with targeting IL-10, CD47 and CD24 could be a novel strategy for the treatment of lung cancer." (PMID 36186906, 2022). "For example, CD24 and Hsp70 interact with each other to regulate the progression of lung cancer." (PMID 34905470, 2021). "Yet, several surface markers have been proposed in the literature including CD24 for pancreatic and lung cancer, CD44 for breast, liver and head and neck cancers, CD133 (or Prominin) used for brain, colorectal, lung and liver cancers, and EpCAM/ESA for colorectal, and pancreatic cancers." (PMID 29391537, 2018). "We then tested two potential biomarkers of H460-derived lung cancer stem cells, CD24 and CD38." (PMID 22592563, 2013).
lung carcinoma (continued). "Thus, CD24 may be a potential marker of invasion and prognosis in lung cancer, and as well as a viable target for treatment of early-stage lung cancer." (PMID 37919766, 2023). "Co-expression of CD24 and Hsp70 may be a prognostic biomarker for lung cancer." (PMID 37919766, 2023). "High levels of CD24 were associated with shortened overall survival (OS) and progression-free interval (PFI), suggesting that CD24 may be a viable target for treatment of lung cancer." (PMID 37187731, 2023). "In addition, HIIT significantly up-regulates the expression levels of CD47 and CD24 in lung cancer tissue, similar to PD-L1, which may also be relevant to the inhibition of macrophage phagocytic activity and the enhancement of tumor immunogenicity." (PMID 36186906, 2022). "Hsp70 upregulates CD24 expression and activates downstream MAPK/ERK signaling, thereby enhancing the metastatic and invasive capacity of lung cancer." (PMID 41195275, 2025). "Several surface markers for lung cancer stemness have been identified, including CD133, CD29, and CD24." (PMID 36547898, 2022). "Expression profiling in human lung cancer cell lines has identified NEDD9 and CD24 as metastasis-promoting genes." (PMID 26418721, 2015). "We analyzed the expression of CD24 and CD38 as two potent biomarkers of lung cancer stem cells and EpCAM and ALDH that are used as biomarkers of a wide range of cancer stem cells." (PMID 22592563, 2013). "Other genes that we chose (e.g., CD24, TACSTD1, TACSTD2, CEACAM1, and PRKCD) are correlated with lung carcinoma or other tumors." (PMID 19874631, 2009). "In this study, 11 lung cancer cell lines and tissue of 89 NSCLC cases were immunohistologically examined for the expression of CD24 protein using a well-characterised monoclonal antibody." (PMID 12610508, 2003). "Similarly, senescent epithelial A549 lung cancer cells and senescent primary human small airway epithelial cells (SAEC) also exhibited elevated CD24 expression relative to their proliferating counterparts." (PMID 36459066, 2023). "Moreover, lung cancer stem cells express “stemness”-related biomarkers, such as CD44, CD24, CA133, CD13, CD90, ABCG2, SOX2, and EPCAM." (PMID 32849930, 2020). "In this study, we found that Apatinib could inhibit the expressions of stemness biomarkers ABCG2, CD24, ICAM-1, OCT4, and SOX2 in lung cancer." (PMID 32849930, 2020). "CD166+, CD133+, CD44+, and CD24+ITGB4+NOTCHhi cells have been labeled as CSCs or TICs in different studies, but few of these studies could be repeated in lung cancer cell lines or samples." (PMID 25965829, 2015). "Interestingly, another expression profiling study of human lung cancer cell lines and mouse lung tumors identified a variety of metastasis-promoting genes, such as VEGF, CD24, and NEDD9 as targets of LKB1 repression in lung cancer." (PMID 26056085, 2015). "According to the real-time PCR detection results, for the surface marker-related genes of lung cancer stem cells, the expressions of CD13 and CD44 were upregulated in the Apatinib group when compared to the control group, whereas the expressions of ABCG2, CD24, and ICAM-1 were downregulated." (PMID 32849930, 2020). "When EGFR-tyrosine kinase inhibitors (TKI)-treated EGFR-mutant cells were cultured in vitro with anti-CD24 antibodies, monocyte-derived macrophages promoted antibody-dependent cell phagocytosis (ADCP), indicating that CD24 may be a therapeutic target for EGFR-mutant lung cancer." (PMID 38279998, 2024). "Although CD133 and CD24 are putative markers for cancer stem cells in human brain and colon cancers, respectively, the present results do not indicate that the residual cells are cancer stem cells because cancer stem cells in human lung cancer have not yet been identified." (PMID 24100792, 2013).
lung carcinoma (continued). "Thus, a single marker may not be sufficient to isolate CSCs, and as a result, several markers are employed together to isolate certain types of CSCs, such as CD44+CD133+CD24+ cancer stem-like cells involved in murine melanoma, CD133+CD34+ melanoma CSCs, and CD133+/nestin+ lung cancer CSCs." (PMID 22558209, 2012). "E xpression of the hub genes HBEGF, GJA4, DDR1, CD24, TBX2, GATA3, and SASH1 did not appear to be prognostic in lung cancer." (PMID 37324026, 2023). "We did not observe any RNA expression for CD24 in H661 and SK-MES cell lines, and no quantifiable CD38 RNA expression was seen in the lung cancer cell lines that were CD38-/low by flow cytometry." (PMID 24094028, 2013). "Unfortunately, endurance exercise did not change the expression levels of CD47 and CD24, and HIIT significantly increased the expression of CD47 and CD24 in lung cancer tissues, suggesting that HIIT may enhance the inhibitory effect of tumor cells on the phagocytosis of TAMs." (PMID 36186906, 2022).